CXCR4 (C-X-C motif chemokine receptor 4)
Diseases named in the same sentence as CXCR4 in open-access papers (continued):
Sharing a sentence is not in itself a finding about the gene and the disease.
leukemia (continued). "For instance, AMD3100, a specific CXCR4 antagonist, enhances the efficacy of chemotherapy by inhibiting SDF1-CXCR4, facilitating the entry of leukemia cells into the cell cycle." (PMID 40114928, 2025). "Multiple cancer cells show elevated expression of CXCR4, including leukemia, T- and B cell lymphoma cells." (PMID 41402431, 2025). "With the described nanobody-based TR-FRET approach, we detected for the first time endogenous CXCR4 homo-oligomers in lymphoma- or leukemia-derived human cell lines and in PBMCs." (PMID 41402431, 2025). "Preclinical studies using a humanized murine leukemia model have demonstrated that CXCR4-directed ERT can effectively eliminate leukemic cells." (PMID 39744224, 2025). "Previous literature has shown that increased CXCR4 on leukemia cells promotes migration of Treg cells toward the leukemic niche, and blocking the CXCR4 axis decreased Treg cells activation and leukemia growth." (PMID 40691440, 2025). "Targeting CXCR4 with antagonists to dislodge leukemia cells from the BM has shown promise, making these cells more vulnerable to treatment." (PMID 39871937, 2024). "More importantly, the bone marrow stromal cell membrane also acted as a CXCR4 antagonism to block the CXCR4/CXCL12-mediated homing of leukemia cells to the bone marrow and infiltration to other organs." (PMID 38689664, 2024). "Mechanism study found that Nrf2 overexpression within MSCs promoted PI3K-AKT/ERK1/2 phosphorylation in the downstream pathway by activating SDF-1/CXCR4 axis, ultimately leading to extramedullary infiltration of leukemia cells." (PMID 39081954, 2024). "A study showed that the CXCR4 antagonist Plerixafor mobilizes leukemia cells, thereby leading to sensitization of cytotoxic therapy and improvement of hematopoietic cell transplantation (HCT)." (PMID 38791414, 2024). "Preliminary evidence shows that when specifically blocking the SDF-1/CXCR4 signaling axis, the migration and invasion ability of leukemia cells can be effectively attenuated, and the changes of Nrf2 in MSCs did not affect the blocking results of the cells." (PMID 39081954, 2024). "Treatment with lenalidomide, an immunomodulatory anticancer drug, inhibits STAT3Y705 phosphorylation induced with IL-10 in healthy T cells, reversing the T-cell dysfunction induced with CLL, indicating the significance of CXCL12/CXCR4 in leukemia treatment." (PMID 38920657, 2024). "Collectively, SDF-1/CXCR four signaling axis is the vital factor related to impact of Nrf2 overexpression in MSCs on promoting leukemia cell invasion, migration and proliferation, and CXCR4 inhibitor AMD3100 can effectively block this process." (PMID 39081954, 2024). "We confirm that MSCs with Nrf2 overexpression induces the phosphorylation in downstream pathways through activating SDF-1/CXCR4 axis, thus enhancing leukemia cell invasion and migration." (PMID 39081954, 2024). "The prognostic significance of CXCR4 expression on leukemia cells in AML patients has been recognized, as varying levels of expression correlate with disease outcomes." (PMID 39871937, 2024). "The proposed mechanism of extramedullary involvement in acute leukemias is altered bone marrow homing and increased peripheral blood dissemination via a chemotactic gradient of SDF-1 with increased CXCR4 expression on the leukemia cells." (PMID 36900239, 2023). "Multiple studies have attempted to make leukemia cells more sensitive to chemotherapeutics by disrupting their interaction using the CXCR4 inhibitor AMD3100." (PMID 37670388, 2023). "A combinatorial treatment with CXCR4 antagonists would therefore be mandatory to overcome the resistance to inhibitor treatment and avoid leukemia relapse." (PMID 37849810, 2023). "In subsequent experiments, we further detected the proliferative signaling pathways of AKT and ERK downstream of the SDF-1/CXCR4 axis in leukemia cells." (PMID 37670388, 2023).
leukemia (continued). "In the present work, IFI6 was found capable of initiating the ERK signaling pathway via the SDF-1/CXCR4 axis, thereby facilitating the leukemia cell multiplication." (PMID 37670388, 2023). "Previously, our research group developed a multivalent protein nanoparticle (T22-PE24-H6) that selectively targets CXCR4-positive leukemia cells." (PMID 36986589, 2023). "The surface expression of CXCR4 was found to be of prognostic relevance in leukemia, as either low expression of CXCR4 was found to be favorable for the treatment outcome, or high expression was associated with a poor prognosis." (PMID 37849810, 2023). "For this reason, studies blocking CXCR4 by mAbs or small molecule have shown a great potential effect on leukemia maintenance and progression." (PMID 36624522, 2023). "Mature B cells express the chemokine receptor CXCR4, which is essential for the process of tumor lymphomagenesis, infiltration, and retention of leukemia cells in the metastatic sites." (PMID 37033927, 2023). "By usingin vitro models and an immunocompetent mouse model, we found that both propofol and sevoflurane lead to a reduction in CXCR4 expression and disruption of adhesion to thrombin-cleaved osteopontin in leukaemia cells." (PMID 38798305, 2022). "Since conventional flow cytometry evaluation showed significant differences between leukemia cells derived from High and Standard-risk patients when two surface markers were analyzed (sGRP78 in combination with CD34, CD38, CD10 or CXCR4)." (PMID 35149705, 2022). "In mice affected with either CXCR4( −) or CXCR4( +) leukemia xenografts, an increased [68Ga]PentixaFor signal was observed in the latter animals." (PMID 35674738, 2022). "Dual-action CXCR4-targeting liposomes were developed and proposed for drug delivery and the simultaneous blockage of the CXCR4/CXCL12 axis for leukemia treatment." (PMID 35337163, 2022). "Evidence indicates that the CXCL12/CXCR4 signaling axis plays a role in cancer biology, in solid tumors as well as in hematological malignancies such as T-ALL, where the CXCL12/CXCR4 signaling regulates the maintenance and progression of leukemia." (PMID 35805156, 2022). "For instance, Calcineurin, a serine‐threonine protein phosphatase and a biomarker of T‐ALL leukemia‐initiating cells, regulates the cell surface expression of CXCR4 in a cortactin‐dependent manner." (PMID 36054080, 2022). "Drug resistance and relapse lead to high mortality in acute myeloid leukemia, and studies have shown that CXCR4 overexpression is highly correlated with poor prognosis and drug resistance in leukemia cells." (PMID 35630929, 2022). "Our results indicated that general anaesthetics reduced the surface CXCR4 expression and the adhesion of leukaemia cells to thrombin cleaved osteopontin (OPN) was reduced." (PMID 38798305, 2022). "We also discuss the potential value of using CXCR4 antagonists as chemosensitizer for conditioning regimens and immunosensitizer for graft‐vs‐leukaemia effects of allogeneic haematopoietic stem cell transplantation." (PMID 34050566, 2021). "The combination of the CXCR4 inhibitor BTK140 with imatinib showed a synergistic effect in the eradication of leukemia cells." (PMID 33435150, 2021). "CXCR4 is expressed on leukaemia cells and its ligand stromal‐derived factor 1 (SDF‐1) is produced by stromal cells in the bone marrow." (PMID 34050566, 2021). "CXCR4 is expressed on leukaemia cells and haematopoietic stem cells (HSCs), and its ligand stromal‐derived factor 1 (SDF‐1) is produced abundantly by stromal cells in the bone marrow (BM)." (PMID 34050566, 2021). "The CXCR4/SDF-1α axis played an essential role in the crosstalk between leukemia cells and BM microenvironment." (PMID 33906294, 2021). "The SDF‐1/CXCR4 axis plays an important role in homing to and retention in bone marrow of leukaemia cells." (PMID 34050566, 2021).
leukemia (continued). "Another study showed that the inhibition of CXCR4 with plerixafor increased leukemia cell mobilization and sensitivity towards nilotinib, but in a different, aggressive murine model, treatment with dasatinib and plerixafor was not superior to dasatinib alone." (PMID 33435150, 2021). "Western blot analysis revealed a decrease specifically in the phosphorylated ERK after AMD3465 treatment, confirming an active CXCR4 signaling cascade in CALM-AF10 expressing leukemia cells." (PMID 35070954, 2021). "The fluorescence intensity of CXCR4 in leukaemia cells was significantly higher in patients with EOI than those without." (PMID 34050566, 2021). "Inhibitors of histone deacetylases extensively downregulated CXCR4 expression at both mRNA and protein levels in leukaemia cell lines and lymphoblasts from patients." (PMID 34050566, 2021). "The SDF‐1/CXCR4 axis plays important roles in homing to and retention in the protective BM microenvironment of malignant leukaemia cells and normal HSCs." (PMID 34050566, 2021). "Evidence suggests that CXCR4 plays a role in leukemia cell migration as well, and one study correlated increased CXCR4 expression on lymphoblasts with a trend toward bulky extramedullary disease in pediatric ALL." (PMID 35070954, 2021). "CXCR4 expression is regulated by multiple mechanisms and the level of CXCR4 expression on leukaemia cells has prognostic indications in patients with acute leukaemia." (PMID 34050566, 2021). "First, the expression of CXCR4 was detected in leukemia cells and normal controls (n = 3), from which CXCR4 was found to be highly expressed to varying degrees in Nalm-6, RS4;11 and primary B-ALL cells (n = 3) (P < 0.05)." (PMID 34733839, 2021). "Herein, we identify a genetically defined a subtype of leukemia, which is characterized by high CXCR4 expression and has an intact CXCR4 signaling pathway." (PMID 35070954, 2021). "Based on their ability to mobilize leukemia cells out of protective BM niches, CXCR4 antagonists have been explored as therapy in combination with cytotoxic drugs, including VEN." (PMID 34771483, 2021). "We find high cell surface expression of the cytokine receptor CXCR4 on leukemia cells expressing the CALM-AF10 oncogenic protein, contributing to the migratory nature of this leukemia." (PMID 35070954, 2021). "Administration of CXCR4 antagonists in conditioning or post‐allo‐HSCT to enhance leukaemia cell eradication by high‐dose chemotherapy or GVL effects was attempted." (PMID 34050566, 2021). "Binding of CXCL12 to CXCR4 on leukemia cells activates multiple proliferative and survival pathways, and high CXCR4 expression on leukemic blasts has been identified as a poor prognostic factor in both ALL and AML." (PMID 35070954, 2021). "It is possible that high CXCR4 expression on the plasma membrane of CALM-AF10 leukemias contributes to the development of extramedullary disease." (PMID 35070954, 2021). "Using human B‐ALL patient‐derived xenograft (PDX) and murine leukaemia models, CXCR4 antagonists have reportedly mobilized ALL cells into PB." (PMID 34050566, 2021). "CXCL12 is the primary ligand for the chemokine receptor CXCR4, found on cell surface of HSCs and some leukemia cells." (PMID 35070954, 2021). "We first established that CALM-AF10 expressing leukemia cells have an active CXCR4 signaling cascade by observing a reduction in phophoERK to ERK after CXCR4 inhibition." (PMID 35070954, 2021). "Taken together, these evidences revealed up-regulating of CXCL12/CXCR4 axis contributed to AML development by promoting leukemia cell proliferation and homing capacity." (PMID 34246314, 2021). "In AML patients, the surface of leukemia cells expresses high levels of CXCR4, which is a key molecule involved in anchoring leukemic HSCs within the bone marrow environment." (PMID 33906294, 2021).
leukemia (continued). "Compared with control mice, extended administration of a CXCR4 antagonist to leukaemic mice resulted in a reduction in leukaemia levels in PB and spleens and in the dissemination of ALL cells to extramedullary sites." (PMID 34050566, 2021). "In this study, we demonstrate that CALM-AF10 translocated leukemias show an increased expression of CXCR4, as well as an increase in CXCL12-stimulated cell migration." (PMID 35070954, 2021). "CXCR4 antagonists can mobilize leukaemia cells from BM to circulation, which render them effectively eradicated by chemotherapeutic agents, small molecular inhibitors or hypomethylating agents." (PMID 34050566, 2021). "Using a murine MLL‐AF9 AML model, blocking CXCR4 was found to reduce Treg accumulation in the leukaemia haematopoietic microenvironment and promote anti‐leukaemic effects of CD8+ T cells, and delay leukaemia progression." (PMID 34050566, 2021). "Anti-CXCR4 antibody-induced apoptosis was also demonstrated as one of the mechanisms of anti-leukemia effects." (PMID 32629802, 2020). "Using the MOLM-14/Luc/GFP xenograft model, mice were administered daily treatment with FLT3 and CXCR4 inhibitors after achieving high levels of leukemia chimerism in the blood." (PMID 32629802, 2020). "In this study, we performed an in vivo pooled CRISPR screen that targeted selected cell surface genes that are upregulated in murine MLL-AF9 (KMT2A-MLLT3) LSC-enriched cells and identified CXCR4 as the top regulator of leukemia-initiating cells." (PMID 32460032, 2020). "We next studied how Cxcr4 disruption affects leukemia cells under physiological conditions by performing a competition assay between GFP+ (sgRNA-expressing) and GFP− cells in vivo." (PMID 32460032, 2020). "Consistent with the transcriptome analysis, in the Cxcr4-disrupted leukemia cells, we observed a significant increase in ROS in both the LSCs (c-Kit+) and the bulk leukemia cells in vivo." (PMID 32460032, 2020). "To assess how Cxcr4 deletion in c-Kit+MLL-AF9 leukemia cells affects the fate of leukemia cells in vivo, we next performed RNA sequencing of sorted Cxcr4 sgRNA-expressing leukemia cells harvested from mice 10 days after transplantation." (PMID 32460032, 2020). "To further characterize how CXCR4 signaling promotes leukemia development, we generated two retroviral vectors expressing murine Cxcr4 mutant cDNAs: Cxcr4D99G and Cxcr4L251P." (PMID 32460032, 2020). "In AML, the activation of CXCR4 is critical for the migration and retention of leukemia cells within the BM, for extramedullary metastasis, chemotherapy resistance, and for the maintenance of minimal residual disease (MRD)." (PMID 32260318, 2020). "Expression of both proteins was detected in the bone marrow, liver, and spleen of the mice, therefore generating a disseminated THP-1 AML model displaying high CXCR4 overexpression in leukemia-involved tissues." (PMID 32295630, 2020). "Given the body of evidence demonstrating that CXCR4 is not only a prognostic marker but also plays a role in leukemia progression, several strategies have emerged to potentially treat AML and ALL via targeting CXCR4." (PMID 33014834, 2020). "When transplanted into immunodeficient mice, both murine and human CXCR4-silenced T-ALL samples showed delayed leukemia onset accompanied by increased host survival, as compared to control shRNA-transduced cells." (PMID 33081391, 2020). "The effects of FtH dysregulation on CXCR4/CXCL12-mediated K562 cell motility extend the meaning of iron homeostasis in the leukemia cell microenvironment." (PMID 32432042, 2020). "Results show that migration is inhibited by siRNA, demonstrating that Src is required for CXCR4-mediated leukemia cell migration toward CXCL12." (PMID 32903764, 2020). "After the discovery of the CXCR4 involvement in leukemia its role in cancer has become a widely studied research topic." (PMID 33096815, 2020).
leukemia (continued). "To investigate this question we used murine bone marrow-derived dendritic cells (BMDCs), as these cells harbor the chemokine receptor CXCR4 and share some common signaling pathways with leukemia stem cells." (PMID 32075106, 2020). "Based on the promising results obtained with pharmacological CXCR4 antagonists, several anti-CXCR4 antibodies have been produced and tested in preclinical models against different types of leukemia, and some of them have entered into clinical trials." (PMID 33081391, 2020). "Results show that migration is inhibited by siRNA, demonstrating that ABL1 is required for CXCR4-mediated leukemia cell migration toward CXCL12." (PMID 32903764, 2020). "The CXCR4 antagonist AMD3100 is used in leukemia and solid tumor treatments to sensitize the cells to chemotherapy." (PMID 33195200, 2020). "The finding that Cxcr4 disruption selectively affects growth and survival of leukemia cells in vivo demonstrates the limitation of in vitro assays to address physiologically relevant dependencies of leukemia cells." (PMID 32460032, 2020). "Together with its ligand CXCL12 (also known as stromal-derived factor 1), CXCR4 plays an important role in tumorigenesis by regulating survival, migration, homing, and interaction of leukemia cells with their microenvironment." (PMID 32581241, 2020). "CXCR4 activation induces leukemia cell trafficking and homing to the bone marrow microenvironment because of the constitutive secretion of CXCL12 by stromal cells in bone marrow." (PMID 33363463, 2020). "Sensitivity to chemotherapy is clearly dependent on Myelodysplastic syndromes-leukemia interactions mediated by chemokines such as the SDF-1/CXCR4 axis, integrins, and E-selectin-mediated adhesion of AML cells to vascular cells." (PMID 33253299, 2020). "Cxcr4 was identified as the top-ranked positive regulator of leukemia cells, with all 5 sgRNAs showing a median depletion of a fold change of more than 2.0 in vivo and with one sgRNA depleted more than 30-fold (5.1-fold depletion in log2 scale)." (PMID 32460032, 2020). "In line with this, gene sets for p38 MAPK signaling and myeloid differentiation were enriched in the Cxcr4-disruption signature in leukemia cells." (PMID 32460032, 2020). "We first validated the importance of Cxcr4 in AML by transducing Cas9+dsRed+MLL-AF9 leukemia cells with two different sgRNA-expressing vectors targeting Cxcr4 and coexpressing GFP." (PMID 32460032, 2020). "The CXCR4-targeted imaging with [68Ga]pentixafor in these lymphoma/leukemia needs to be further investigated." (PMID 32757068, 2020). "We sequentially transduced MLL-AF9 leukemia cells with Cxcr4 sgRNA_b coexpressing tRFP657 and Cxcr4 cDNAs coexpressing GFP, which resulted in restored CXCR4 expression on the cell surface." (PMID 32460032, 2020). "CXCL12/CXCR4 antagonists have shown encouraging results in reducing the enhanced survival and proliferation of leukemia cells and sensitizing leukemia cells to chemotherapy." (PMID 32660524, 2020). "Although the majority of the mice in the control group developed leukemia, only two mice transplanted with leukemia cells expressing Cxcr4 sgRNAs developed leukemia." (PMID 32460032, 2020). "Cxcr4 was identified as the top positive regulator of MLL-AF9 leukemia cells, with all five Cxcr4 sgRNAs being depleted in vivo." (PMID 32460032, 2020). "We also identified a positive correlation between the FLT3-ITD MR and the CXCR4 RFI on the surface of leukemia cells (r = 0.588, P ≤ 0.0001)." (PMID 31434952, 2019). "The activation of the SDF-1/CXCR4 axis is a critical event for the migration and retention of leukemia cells within BM, for extramedullary colonization and for the maintenance of minimal residual disease (MRD), as demonstrated in acute myeloid leukemia." (PMID 31346528, 2019). "CXCL12 and CXCR4 serve as prognostic markers in various leukaemia’s with the expression of CXCR4 being highest in promyelocytic leukaemia, myelomonocytic AML and B-lineage ALL." (PMID 31139016, 2019).